UBALD1 (UBA like domain containing 1)
Synonyms: FAM100A; PP11303
Tractability: No criterion of Open Targets' tractability assessment is met for any kind of drug.
Gene: Protein-coding gene on chromosome 16 (4,608,883 to 4,615,027, reverse strand). Ensembl gene ENSG00000153443.
Subcellular location (Human Protein Atlas): Cytosol; Nucleoplasm; Cell Junctions
Gene Ontology:
Molecular function: protein binding
Genetic constraint (gnomAD): Loss-of-function variants: 5 observed, 10.43 expected, observed/expected ratio (o/e) 0.48, 90% interval 0.25 to 1.01. The synonymous counts are far from expectation, so gnomAD's model fits this gene poorly and the ratio says little. Missense variants: 216 observed, 188.2 expected, observed/expected ratio (o/e) 1.15, 90% interval 1.03 to 1.28. Synonymous variants: 144 observed, 88.62 expected, observed/expected ratio (o/e) 1.62, 90% interval 1.42 to 1.86.
Homologues: Orthologues: chimpanzee UBALD1 (100% identical), macaque UBALD1 (99% identical), dog UBALD1 (95% identical), guinea pig UBALD1 (94% identical), rat Ubald1 (94% identical), mouse Ubald1 (92% identical), rabbit UBALD1 (61% identical). Paralogues in human: UBALD2 (61% identical).
Diseases named in the same sentence as UBALD1 in open-access papers:
UBALD1 is named in the same sentence as 4 diseases in open-access papers, as found by Europe PMC text mining. Sharing a sentence is not in itself a finding about the gene and the disease. The quoted sentences say what the papers report.
thyroid cancer (4 papers, 2019 to 2022). "This method was validated by stably transfecting two standard human thyroid cancer cell lines (BCPAP and 8505C) with four distinct genes (DDX19B, NEMP1, PANK2, UBALD1) and profiling their transcriptome before and after the transfection." (PMID 33302383, 2020). "Expression data for the GMR Theory validation on thyroid cancer cell lines BCPAP and 8505C were collected from GSE97031 (transfection with NEMP1), GSE97028 (DDX19B), GSE97030 (PANK2) and GSE97427 (UBALD1)." (PMID 31349573, 2019). "Nonetheless, we validated the relationship between the GCH score and the transcriptomic consequences of manipulating the gene expression by stably transfecting DDX19B, NEMP1, PANK2, and UBALD1 on the papillary (BCPAP) and anaplastic (850C) human thyroid cancer cell lines." (PMID 34209090, 2021).
diabetes (1 paper, 2020). "In addition, we identified nine genes (CABIN1, CKS1B, C19orf60, SDR39U1, SLC31A1, DNAJA4, ZC3H8, OTUD3 and UBALD1) not previously associated with diabetes, but that are known to be involved in processes potentially linked to β-cell dysfunction, such as cell turnover, oxidative stress and ER stress." (PMID 33575641, 2020).
cancer (1 paper, 2020). A tumor composed of atypical neoplastic, often pleomorphic cells that invade other tissues. "Although DDX19B and PANK2 (but not NEMP1 and UBALD1) were synergistically expressed with SPINT2 in PTC, there are no reports relating these genes with SPINT2 in any form of cancer." (PMID 32887258, 2020).
UBALD1 also shares sentences with these, for which no sentence is quoted: lymphoma (1 paper).